VWF (von Willebrand factor)
Diseases named in the same sentence as VWF in open-access papers (continued):
Sharing a sentence is not in itself a finding about the gene and the disease.
autonomic dysfunction (1 paper, 2015). "It has been proposed that cisplatin is associated with vascular injury, platelet-aggregation alterations, augmented serum levels of vWF:Ag, and autonomic dysfunction." (PMID 26425644, 2015).
benign brain tumors (1 paper, 2016). "In another series, VWF levels were significantly higher in 30 patients with malignant brain tumors as compared with 30 patients with benign brain tumors 32 but no regression analysis was performed to ascertain their prognostic value." (PMID 27236861, 2016).
bladder cancer (1 paper, 2023). "Compared with the expression levels in SV-HUC-1 uroepithelial cells, ATP2A3 and VWF were meaningfully low expressed in 4 bladder cancer cell lines (T24, 253J-BV, EJ, UMUC3), while P4HB were high." (PMID 37091788, 2023).
bone cancer (1 paper, 2018). A primary or metastatic malignant neoplasm affecting the bone or articular cartilage. "It has been reported that vWF is involved in cell death, for example, vWF would be able to control bone cancer cells apoptosis by controlling the binding of osteoprotegerin to TRAIL." (PMID 30279208, 2018). "Contradictorily, vWF was also reported to be involved in bone cancer cell apoptosis by inducing the binding of osteoprotegerin to TRAIL, implying a multiple facet of vWF in cancer progression." (PMID 30279208, 2018).
bronchogenic carcinoma (1 paper, 2024). A lung carcinoma arising from the bronchial epithelium. "Of the four cases, two involved primary bronchogenic carcinomas, and both patients had undergone cisplatin chemotherapy, which is believed to promote a prothrombotic state from elevation of von Willebrand factor levels, hypomagnesemia-associated vasospasm, and LV dysfunction." (PMID 38730499, 2024).
brucellosis (1 paper, 2024). Brucellosis is a bacterial infection that spreads from animals to people via unpasteurized dairy products or by exposure to contaminated animal products or infected animals. "In our study, we observed elevated levels of endothelial injury markers, including von Willebrand factor (VWF), VCAM-1, and ICAM-1, in patients with acute and chronic Brucellosis." (PMID 39872944, 2024).
cerebral (1 paper, 2022). "The combination of VWF inactivation and high pulse pressure may trigger cerebral bleeding, suggesting that a VWF multimer defect could also increase the risk of CMBs in the setting of high pulse pressure." (PMID 35722876, 2022).
cerebral artery occlusion (1 paper, 2018). "Using the focal ischemia mouse model, in which middle cerebral artery occlusion is largely VWF‐dependent, they confirmed that VWF‐rich thrombi are t‐PA‐resistant." (PMID 29108103, 2018).
cholestasis (1 paper, 2023). Impairment of the bile flow caused by obstruction within the liver, or outside the liver in the bile duct system. "Studies of other hepatopathologies indicate an interplay between cholestasis, tissue factor (TF), and von Willebrand factor (VWF)." (PMID 36769887, 2023).
chondrodysplasia (1 paper, 2008). "Although matrilin-3 is the only matrilin family member that has been associated with chondrodysplasia so far, more and more point mutations within the vWF A domain of matrilin-3 have been reported to cause MED." (PMID 18518980, 2008).
chronic GVHD (1 paper, 2023). "As a further proof of the concept that endothelial damage is a major contributor to chronic GVHD pathogenesis, previous studies have shown that VWF is observed during chronic GVHD episodes, and more importantly, VWF levels correlate with disease activity and severity." (PMID 36765638, 2023).
chronic lymphocytic leukaemia (1 paper, 2008). "EST accession [GenBank:AI380234] hit CD93 that is from a B-cell, chronic lymphocytic leukaemia flow-sorted cell line (NCI_CGAP_CLL1), while vWF hit a non-endothelial EST from the NCI_CGAP_Br4 library [GenBank:AA721546]." (PMID 18394197, 2008).
chronic pancreatitis (1 paper, 2018). A chronic inflammatory process causing damage and fibrosis of the pancreatic parenchyma. "Factor VIII, D-dimers, von Willebrand factor, free tissue factor pathway inhibitor and microvesicle-tissue factor (MV-TF) activity were higher in PDAC patients compared to patients with IPMN or chronic pancreatitis." (PMID 29899870, 2018).
coronary artery spasm (1 paper, 2021). "Long-term smoking can cause coronary artery vasodilation, coronary artery endothelial damage, coronary artery spasm, severity of stenosis, increase of platelet aggregation, von Willebrand factor, and aggravate the formation of coronary atherosclerotic plaque." (PMID 33969126, 2021).
coronary atherosclerosis (1 paper, 2025). Atherosclerosis of the coronary vasculature. "Consistently, Mihyawi and colleagues observed a lower prevalence and risk of CAD in VWD patients compared to controls, providing epidemiological support for the pathogenic role of the vWF in coronary atherosclerosis." (PMID 41007843, 2025). "Advanced intravascular imaging techniques, such as intravascular ultrasound (IVUS), have provided valuable mechanistic insights into the link between the vWF and coronary atherosclerosis." (PMID 41007843, 2025).
Dent disease (1 paper, 2024). Dent disease is a rare genetic renal tubular disease characterized by manifestations of proximal tubule dysfunction. "VWF plays an essential role in regulating the balance between blood clotting and bleeding, and the CLCX5 gene is related to Dent disease, while the correlation between both genetic mutations and the occurrence of disease has not been found in the literature." (PMID 38357518, 2024).
diabetic neuropathy (1 paper, 2022). A chronic, pathological complication associated with diabetes mellitus, where nerve damages are incurred due to diabetic microvascular injury involving small blood vessels that supply these nerves, resulting in peripheral and/or autonomic nerve dysfunction. "Comparison between controls and patients with diabetic neuropathy before and after capsaicin 8% patch application showed significantly higher levels of vWF in DPN in a different cohort of PDPN/NPDPN patients." (PMID 36388188, 2022). "No changes in von Willebrand Factor (vWF) were observed after treatment with capsaicin 8% patch in patients with non-Painful Diabetic Neuropathy (NPDPN Q+SOC)." (PMID 36388188, 2022).
Ebola (1 paper, 2009). "When comparing Lossi sanctuary and periphery, homogeneity tests were significant for three loci (D1s533 n = 17, D4s243 n = 20, and D6s474 n = 19) before Ebola and three loci after (D4s243, D16s2624 n = 18and vWF n = 21)." (PMID 20020045, 2009).
Fabry disease (1 paper, 2024). Fabry disease (FD) is a progressive, inherited, multisystemic lysosomal storage disease characterized by specific neurological, cutaneous, renal, cardiovascular, cochleo-vestibular and cerebrovascular manifestations. "Notably, elevated levels of C5a and P selectin have been detected in the peripheral blood of individuals with Fabry disease as well as increased secretion of both vWF and P selectin in both in vitro and in vivo mouse models of Fabry disease." (PMID 39596318, 2024).
Fanconi anemia (1 paper, 2021). Fanconi anemia (FA) is a hereditary DNA repair disorder characterized by progressive pancytopenia with bone marrow failure, variable congenital malformations and predisposition to develop hematological or solid tumors. "Increased VWF has been implicated in vascular dysfunction and decreased UBE2T in Fanconi anemia, and acute deregulated expression of these genes may have contributed to the adverse outcomes observed within 2 weeks of Zeb1/2 deletion." (PMID 34550965, 2021).
fatty liver (1 paper, 2019). "Of note, patients with fatty liver have been found to have a higher level of vWF than those without; an increasing level of vWF has been found to be significantly associated with metabolic features of NAFLD patients." (PMID 31800606, 2019).
Fever (1 paper, 2012). Body temperature elevated above the normal range. "The endothelium-tropic spotted fever rickettsia R. rickettsii (Rocky Mountain spotted fever) and R. conorii (Mediterranean spotted fever) induce a procoagulant state, with upregulation of TF, downregulation of TM and release of both PAI-1 and VWF in cultured human endothelial cells." (PMID 22192733, 2012).
ganglioglioma (1 paper, 2023). A well differentiated, slow growing neuroepithelial neoplasm composed of neoplastic, mature ganglion cells and neoplastic glial cells. "Co-expression of CD34, PAX6, SOX2, and MSI1 (after stringent counter selection against vascular cells using PECAM1, VWF, DCN, and COL1A2), was particularly strongly associated with ganglioglioma neoplastic cell stemness." (PMID 36966348, 2023).
gastric tumor (1 paper, 2023). "Compared with benign tissues, the CTLA4 and ENTPD2 were highly expressed in gastric tumor tissues, while the AKR1B1, CLDN6, EMB, GPR15 and VWF were highly expressed." (PMID 37066015, 2023).
gliosarcoma (1 paper, 2025). A rare histological variant of glioblastoma (WHO grade IV) characterized by a biphasic tissue pattern with alternating areas displaying glial and mesenchymal differentiation (WHO). "In addition to podoplanin, studies involving gliosarcoma models have demonstrated the upregulation of other proteins such as glial fibrillary acidic protein (GFAP) and von Willebrand factor (vWF)." (PMID 40806177, 2025).
gout (1 paper, 2025). A condition characterized by painful swelling of the joints, which is caused by deposition of urate crystals. "Given the established roles of MPO in hypochlorous acid generation and vWF in NET stabilization, these data suggest that QFHZ might attenuate gout recurrence by indirectly influencing NET-related inflammation." (PMID 41190022, 2025).
Granuloma (1 paper, 2022). A compact, organized collection of mature mononuclear phagocytes, which may be but is not necessarily accompanied by accessory features such as necrosis. "Immunoreactivity to vWF was present in some rare sinusoids, in portal and central veins when they were associated with the parasite egg, or with surrounding inflammatory infiltrates and, in some cases, in wide-lumen blood vessels present in the peripheral zone of mature granulomas." (PMID 36091027, 2022). "In the schistosomal liver, there are vessels with activated endothelium that express vWF, in addition to the appearance of new vessels in the middle and peripheral zones of mature granulomas." (PMID 36091027, 2022).
hand and foot syndrome (1 paper, 2018). "Unwanted effects of sorafenib treatment, which included hand and foot syndrome and avascular femur necrosis, were observed 4 months after the MKI installation, while at the laboratory level, high von Willebrand factor activity (388%) was documented." (PMID 29304116, 2018).
Hemoptysis (1 paper, 2025). Coughing up (expectoration) of blood or blood-streaked sputum from the larynx, trachea, bronchi, or lungs. "In most cases, adverse events were manageable and caplacizumab was continued, although one patient with pneumopathy-associated hemoptysis required infusions of factor VIII and VWF concentrates." (PMID 40235949, 2025).
hepatic angiosarcoma (1 paper, 2019). "Staining against endothelial markers, such as vWF, CD31, or CD34, is commonly used for the diagnosis of human hepatic angiosarcoma." (PMID 31095587, 2019).
hepatitis B (1 paper, 2023). "Previous data from patients with hepatitis B, however, demonstrated that histological VWF expression in the liver correlated with PH and disease severity." (PMID 37605068, 2023).
Hermansky-Pudlak syndrome (1 paper, 2025). Hermansky-Pudlak syndrome (HSP) is a multi-system disorder characterized by oculocutaneous albinism, bleeding diathesis and, in some cases, neutropenia, pulmonary fibrosis, or granulomatous colitis. "Specifically, depletion of the Hermansky-Pudlak syndrome (HPS) protein-6 led to misshaped WPB and an impaired tubulation of VWF, which is required for the tight packing of VWF inside WPB and thus, their rod-shaped morphology." (PMID 40612111, 2025).
hyperuricemia (1 paper, 2020). An abnormally high level of uric acid. "The serum NO level and TAC were lower in the HUA group than those in the MS model, and the concentration of the endothelial injury marker vWF and H2O2 level was remarkably higher, indicating that endothelial injury occurred in the MS model, and hyperuricemia exacerbated the injury." (PMID 32565731, 2020). "In a MS/hyperuricemia model, nitric oxide (NO) production was decreased, followed by a decrease in total antioxidant capacity (TAC), and the concentration of the endothelial injury marker von Willebrand factor (vWF) in the serum was increased." (PMID 32565731, 2020).
Inguinal hernia (1 paper, 2024). Protrusion of the contents of the abdominal cavity through the inguinal canal. "The IVW method indicates that genetically-predicted POMC (OR [95%]=0.716 [0.5287 to 0.9717], p = 0.0319) and VWF (OR [95%]=0.9988 [0.9976 to 0.9999], p = 0.0363) possess a clear protective effect on unilateral inguinal hernia." (PMID 38591204, 2024).
Intestinal tumour (1 paper, 2003). "Intestinal tumour sections from each treatment group were stained for VWF to determine if MMPI or COX-2I used alone or in combination could alter angiogenesis." (PMID 12778076, 2003).
intracranial hemorrhage (1 paper, 2025). Bleeding within the SKULL, including hemorrhages in the brain and the three membranes of MENINGES. "Our findings indicated a decrease in vWF levels in patients with s‐HT, which aligns with existing literature suggesting that patients with intracranial hemorrhage tend to have lower vWF levels." (PMID 40135640, 2025).
intrahepatic cholangiocarcinoma (1 paper, 2025). A carcinoma that arises from the intrahepatic bile duct epithelium in any site of the intrahepatic biliary tree. "We encountered a patient with intrahepatic cholangiocarcinoma and VWD who was successfully treated with anatomical hepatectomy by robotic-assisted laparoscopic surgery under perioperative replacement therapy with a VWF- or FVIII-containing concentrate." (PMID 40755903, 2025). "We encountered a patient with intrahepatic cholangiocarcinoma (ICC) and VWD who successfully underwent an anatomical hepatectomy via robotic-assisted laparoscopic surgery under perioperative replacement therapy with a VWF- or FVIII-containing concentrate." (PMID 40755903, 2025).
intrauterine growth restriction (1 paper, 2021). "Thus, in pregnancies with intrauterine growth restriction that occurs when a fetus does not reach its growth potential, the expression of vWf is higher, although not at a statistically significant level." (PMID 33578631, 2021).
Intraventricular hemorrhage (1 paper, 2025). Bleeding into the ventricles of the brain. "His neonatal course was complicated by Grade 1 intraventricular hemorrhage and one traumatic soft tissue bleed treated with plasma-derived von Willebrand factor/FVIII concentrate (the CFC product available at the treating hospital in Saipan) for two ED." (PMID 41255845, 2025).
invasive carcinoma (1 paper, 2002). A carcinoma that is not confined to the epithelium, and has spread to the surrounding stroma. "In DCIS associated with invasive carcinoma, there were significantly greater numbers of CD34+ and CD141+ vessels and fewer staining for vWF compared with pure DCIS." (PMID 11953822, 2002). "In normal lobules surrounding cases of pure DCIS, MVD was highest when stained with vWF, whereas the normal lobules surrounding areas of invasive carcinoma and DCIS had the highest MVD with CD34." (PMID 11953822, 2002). "It is of interest in this context that the normal lobules from cases of invasive carcinoma exhibited significantly lower numbers of vWF+ vessels than those from cases of pure DCIS." (PMID 11953822, 2002). "In DCIS with invasive carcinoma, in common with cases of pure DCIS, there was an increase above normal in CD31, CD34 and CD141 but a decrease in vWF immunopositive vessels." (PMID 11953822, 2002). "Periductal vascular density and phenotype were determined using morphometry and a panel of anti-endothelial antibodies (von Willebrand factor, CD31, CD141 and CD34) and related to the presence of invasive carcinoma and other histological features." (PMID 11953822, 2002).
lentivirus infection (1 paper, 2022). Virus diseases caused by the Lentivirus genus. "We knockdown the expression of ANRIL in endothelial cells under IS stimulation, and the results showed that compared with scramble, ANRIL shRNA lentivirus infection (Sh-ANRIL) lead to eNOS expression upregulated, while the expression of VCAM-1 and vWF decreased." (PMID 35906216, 2022).
leprosy (1 paper, 2018). Leprosy is a chronic infectious disease affecting primarily the skin and peripheral nervous system. "We demonstrated that leprosy MB patients develop a procoagulant status due to high levels of plasmatic fibrinogen, anti-cardiolipin antibodies, von Willebrand factor and soluble tissue factor." (PMID 29565968, 2018). "We characterize the nature of leprosum clot, describing a panel of serum proteins which are up-regulated in multibacilary leprosy patients, such as D-dimers, anti-cardiolipin, von Willebrand factor, soluble tissue factor, C4 and IHRP." (PMID 29565968, 2018).
leukopenia (1 paper, 2021). "Labs were notable for leukopenia, elevated lactate dehydrogenase (LDH) and Von Willebrand Factor (VWF) antigen and positive anti-nuclear antibody (ANA)." (PMID 34118936, 2021).
Lipedema (1 paper, 2023). Disorder of adipose tissue characterized by symmetric and bilateral enlargement of the lower extremities due to abnormal deposition of subcutaneous fat often in obese women. "Furthermore, studies have also shown that vWF controls the levels of ANG2 secreted by activated ECs via VEGFR2, resulting in blood vessel disruption and angiogenesis, consistent with the phenotype detected in lipedema tissue." (PMID 37686378, 2023).
lung adenoma (1 paper, 2013). A benign, well circumscribed epithelial neoplasm that arises from the bronchus or the lung parenchyma. "Multiple differences between the three cell types (malignant human lung adenoma H460 cells, rat embryonic aortic smooth muscle line A7R5, and primary human brain vascular smooth muscle cells) used here make it difficult to unravel the mechanisms underlying ligand specific vWF action." (PMID 24086636, 2013).
lupus nephritis (1 paper, 2015). Glomerulonephritis in the context of systemic lupus erythematosus. "Previous study reported that treatment with corticosteroids or mycophenolate acid reduced VWF levels in patients with lupus nephritis, suggesting that these immunosuppressive drugs improve endothelial function." (PMID 26229221, 2015).
macular holes (1 paper, 2017). A hole in the macula of the retina. "Thyroxine-binding globulin, kallistatin, hepatocyte growth factor activator, von Willebrand factor, and glyceraldehyde-3-phosphate dehydrogenase were increased in both PDR versus macular holes and NPDR versus macular holes." (PMID 28452939, 2017).
malignant hypertension (1 paper, 2019). Severe hypertension that is characterized by rapid onset of extremely high blood pressure and hypertension-mediated organ damage. "This is in accordance with correlations found between VWF activation factor and VWF:Ag in previous studies in patients with a first STEMI (r = 0.58) and malignant hypertension (r = 0.62)." (PMID 30759116, 2019).